TIGIT (T cell immunoreceptor with Ig and ITIM domains)
Diseases named in the same sentence as TIGIT in open-access papers (continued):
Sharing a sentence is not in itself a finding about the gene and the disease.
leukoplakia (1 paper, 2024). A white patch or plaque on a mucous membrane that cannot be characterized clinically or pathologically as any other disease. "Finally, we found that NK/T cell subgroups in the HNSCC group highly expressed marker genes of depleted T cells such as CTLA4, LAG3, TIGIT, and HAVCR2, indicating that the inhibition degree of NK/T cells in the HNSCC group was stronger than that of leukoplakia." (PMID 38582791, 2024).
Myelopathy (1 paper, 2016). Myelopathy is an descriptive term, referring to pathology leading to a neurologic deficit related to the spinal cord. "Furthermore, TIGIT was highly expressed on ATL cells and HTLV-1 infected cells from HTLV-1-associated myelopathy/tropical spastic paraparesis (HAM/TSP) patients." (PMID 26735971, 2016).
nasopharyngeal carcinoma (1 paper, 2023). A carcinoma arising from the nasopharyngeal epithelium. "We aimed to investigate the co-expression of TIM-3 with TIGIT or 2B4 on peripheral blood CD8+ T cells from patients with locally advanced nasopharyngeal carcinoma." (PMID 36913701, 2023). "TIM-3/TIGIT and TIM-3/2B4 co-expression was upregulated on peripheral blood CD8+ T cells from patients with nasopharyngeal carcinoma." (PMID 36913701, 2023).
nephritis (1 paper, 2024). Inflammation of renal tissue. "Our research identified high expressions of PD1, CTLA4, TIM3, and TIGIT on T cells were correlated with disease activity, nephritis, and treatment response downregulation in SLE." (PMID 38650001, 2024).
oesophageal adenocarcinoma (1 paper, 2022). "•Glucose deprivation and hypoxia upregulate PD-1 and TIGIT on the surface of oesophageal adenocarcinoma (OAC) cells in vitro." (PMID 35245832, 2022).
Opportunistic infection (1 paper, 2023). An infection that is caused by a pathogen that would generally not be able to cause an infection in a host with a normal immune system. "The TIGIT+FOXP3+Treg subset (TIGIT+Tregs) exerts robust suppressive activity on cellular immunity and predisposes septic individuals to opportunistic infection." (PMID 37604833, 2023).
penile cancer (1 paper, 2025). A primary or metastatic malignant neoplasm that affects the penis. "In the present study, we have evaluated the expression and prognostic value of PD-L1, as well as two additional immune checkpoint proteins, TIGIT and CD155, along with HPV status, in a cohort of men with lymph node metastasized penile cancer." (PMID 40822998, 2025). "We report on high expression of immune checkpoint proteins PD-L1, TIGIT, and CD155 in men with lymph node metastasized penile cancer." (PMID 40822998, 2025). "Therefore, the primary aim of this study was to examine the expression of PD-L1, TIGIT, and CD155, and the HPV status in the primary tumors from penile cancer patients with indication for perioperative oncological treatment according to the present Swedish national guidelines." (PMID 40822998, 2025).
peripheral T cell lymphoma (1 paper, 2019). "In an L-HES patient who progressed to peripheral T cell lymphoma, the malignant transformation identified increases in the expression of CDCA7, TIGIT, and TOX, which are highly expressed in SS, suggesting that these genes contribute to neoplastic transformation." (PMID 31489115, 2019).
pituitary tumor (1 paper, 2021). A benign or malignant neoplasm affecting the pituitary gland. "Whether the secretion of hormones in functional pituitary tumors can also affect the expression of TIGIT and the coinhibition of TIGIT and other targets can affect the immunotherapy of pituitary tumors are two problems facing us at present." (PMID 34447484, 2021).
progeria (1 paper, 2025). "Many genes, such as CCL2 and UCP2, were upregulated in progeria whilst CD27, CD28, and TIGIT were dysregulated in senescent cells." (PMID 40343591, 2025).
psychological distress (1 paper, 2024). "This study examined associations between symptoms of maternal prenatal psychological distress and percentages of maternal circulating FoxP3+ Tregs and six Treg subpopulations expressing Helios, CD45RA, CTLA-4, PD-1, TIGIT, or TIM-3." (PMID 38016492, 2024).
renal fibrosis (1 paper, 2022). A final common manifestation of a wide variety of chronic kidney diseases characterized by glomerulosclerosis and tubulointerstitial fibrosis. "Moreover, the CD226+TIGIT– T cell population was associated with reduced Treg purity and suppressive capacity after expansion, and CD226 deficiency on Treg cells can aggravate renal fibrosis." (PMID 35587519, 2022).
skin inflammation (1 paper, 2023). "In that study, TIGIT expression was increased on the AD patients’ CD4+ T cells to impede chronic skin inflammation, and TIGIT expression may be impaired in some AD patients, leading to the deterioration of skin inflammation." (PMID 36993982, 2023).
Stroke (1 paper, 2025). Sudden impairment of blood flow to a part of the brain due to occlusion or rupture of an artery to the brain. "Other inhibitory checkpoint pathways such as PD-1, TIM-3, LAG-3, and TIGIT likely contribute to T cell regulation after stroke but were beyond the scope of this focused analysis and should be addressed in future studies." (PMID 41373643, 2025).
systemic candidiasis (1 paper, 2024). "In a systemic candidiasis model, TIGIT-KO mice exhibited improved survival and reduced body weight loss compared to WT mice." (PMID 39109867, 2024).
T cell lymphoma (1 paper, 2019). "In an in vivo study, NK cells isolated from TIGIT-transgenic mice produced reduced amounts of IFN-γ after incubation with Yac-1 cells (murine T cell lymphoma cell line), while NK cells isolated from TIGIT−/− mice produced increased amounts of IFN-γ." (PMID 31681269, 2019).
tumor (1,399 papers, 2014 to 2026). "In our cohort, tumors classified as MSI on the basis of IHC assessment of MMR protein loss showed significantly higher TIGIT protein levels compared with the MSS tumor group." (PMID 41596586, 2026). "In dMMR CRC, both TIGIT protein and mRNA levels were higher in tumor tissue than in adjacent mucosa and were associated with a higher TNM stage." (PMID 41596586, 2026). "Elevated TIGIT expression has been documented in the tumor microenvironment across various malignancies, with TIGIT expression on TILs linked to unfavorable survival outcomes." (PMID 39939322, 2025). "TIGIT and the accumulation of regulatory T cells in tumor tissues are primarily associated with tumor progression and reduced effector functions against malignant cells, ultimately leading to immune escape of tumor cells." (PMID 40574024, 2025). "TIGIT impacts adenosine receptor signaling in T-cells, interferes with T-cell energy metabolism, and is associated with the kynurenine pathway in tumor cells, thereby altering the TME and T-cell-mediated immunity against tumors." (PMID 40236693, 2025). "Given the remarkable responses observed in the animal model treated with anti-PD-1 and anti-TIGIT antibodies, we were interested in determining the mechanism of the increased tumour response associated with this combination treatment." (PMID 39939955, 2025). "In vitro co−culture assays demonstrate that direct tumor–T cell contact suffices to induce TIGIT and PD−1 upregulation, establishing a causal link between tumor−derived factors and the exhausted phenotype." (PMID 40799645, 2025). "Clinical investigations have demonstrated that elevated TIGIT expression on NK cells is associated with functional exhaustion and an unfavourable tumour prognosis." (PMID 41429765, 2025). "The anti-tumor effect is associated with down-regulation of mRNA relating to several IC molecules, including TIGIT, PD-1 and LAG-3." (PMID 40890162, 2025). "Our analysis has revealed a positive correlation between ETS1 and the immune checkpoints PDCD1 and TIGIT, which are linked to immune dysfunction and tumour progression." (PMID 41162582, 2025). "Highly expressed on diverse tumour cells and tumour-associated myeloid cells, TIGIT engages with its counterpart on CD8+ T cells and NK cells, providing inhibitory signals that suppress antitumour immunity." (PMID 40994140, 2025). "Another CAR-T-cell therapy study revealed that decreased cytotoxic T cells, increased myeloid-derived suppressor cells, and TIGIT overexpression in tumor cells and T cells were associated with MCL relapse after CAR-T-cell therapy." (PMID 40876452, 2025). "This review will first discuss the mechanisms underlying the inhibitory effect of TIGIT on tumor-related immunity and combination immunotherapeutic strategies, then discuss current approaches targeting TIGIT beyond mAbs monotherapy." (PMID 40890162, 2025). "In contrast, resistance is associated with upregulation of TIM3, LAG3, TIGIT, and PD-1 expression on T cells, and infiltration of the tumor with immunosuppressive TREM2+ macrophages and monocytes." (PMID 40027748, 2025). "TIGIT expression is associated with T-cell exhaustion, and blocking it can restore T-cell functionality and increase anti-tumor immune responses." (PMID 40075661, 2025). "Meanwhile, researchers also observed down-regulation of immunosuppressive genes in tumor-associated Tregs after Fc-active anti-TIGIT antibody administration, facilitating the efficacy of combination therapy." (PMID 40890162, 2025). "No promising circulating immune markers were found, but increased T reg, effector CD8 + T cells and NK cells in the tumour microenvironment were associated with better anti-tumour response in anti-PD-1 and anti-TIGIT treated mice." (PMID 39939955, 2025). "Further exploration of tumor‐associated immune checkpoints and the risk model is underway, revealing the high expression of TIGIT, PDCD1, and PDCD1LG2 in the low‐risk group." (PMID 38546286, 2025).
tumor (continued). "TIGIT was originally described as an inhibitory receptor of T cells, but we and others recently detected its expression also on tumor-associated NK cells and macrophages." (PMID 40274631, 2025). "Deletion of TIGIT from immune effector cells is a promising approach to protect these cells from tumour-associated inhibitory signals but cannot enhance the effect of GD2-CAR-NK-92 cells." (PMID 40317320, 2025). "Inhibition of tumor growth has been associated with reduced expression of the immune checkpoint molecule TIGIT." (PMID 41048344, 2025). "In metastatic melanoma, a high TIGIT/CD226 ratio in tumor Tregs is linked to increased CD25hiFoxp3+Treg cell frequencies and unfavorable clinical responses following ICI therapies." (PMID 39349829, 2024). "Previous studies suggested that reduced tumor burden and survival benefits were found in TIGIT-deficient mice." (PMID 38229100, 2024). "Our further intercellular communications analysis revealed a pronounced enrichment of the TIGIT-NECTIN2 interaction between the tumor-associated macrophages (TAMs) and CD8+ T cells within the solid tumor pattern." (PMID 39474422, 2024). "A second key effect of Fc-active anti-TIGIT antibodies was the induction of a memory-like gene program and downregulation of the gene program associated with exhausted effectors in tumour CD8+ T cells." (PMID 38418879, 2024). "NECTIN2—TIGIT interaction has been reported in other solid tumors, underlining its universality in tumor microenvironments." (PMID 38181797, 2024). "In human CRC, tumor-infiltrating NK cells showed high TIGIT expression that is associated with their dysfunction." (PMID 39126041, 2024). "Next, we assessed the effects of anti-TIGIT Fc variants on tumour-infiltrating and blood leukocytes using scRNA-seq." (PMID 38418879, 2024). "The TIGIT gene encodes T-cell immunoglobulin and immune receptor tyrosine inhibitory motif domain (TIGIT) receptors, which can promote tumor cell immune evasion." (PMID 38464517, 2024). "TIGIT expression on tumor-infiltrating T cells has been associated with T-cell exhaustion, a state of functional impairment that limits anti-tumor immune responses." (PMID 38017389, 2023). "TIGIT has been implicated in tumor immunosurveillance, and its role is analogous to that of PD-1 in tumor immunosuppression because it is overexpressed in tumor antigen-specific CD8+ T cells and CD8+ TILs and is often coexpressed with PD-1." (PMID 36960057, 2023). "Meanwhile, the expression of LAG3 and TIGIT in this group is relatively high, combined with higher tumor mutation burden (TMB) and microsatellite instability (MSI), which suggests a better response to immune checkpoint inhibitors." (PMID 35801342, 2023). "Its expression has been implicated in tumour immunosuppression, as its interaction with TIGIT or CD96-positive T lymphocytes and NK cells leads to immune exhaustion and reduced interferon-γ secretion." (PMID 37519808, 2023). "TIGIT knockout results in the loss of anti-tumour T and NK cell suppression, and this has been shown in murine models, without the added burden of high-grade autoimmune sequelae." (PMID 37325585, 2023). "TIGIT expression in the tumor microenvironment (TME) has previously been associated with poor outcomes following chemoradiotherapy in patients with cancer." (PMID 35794399, 2023). "Another mechanism by which TIGIT is implicated in tumor progression is via its competitive and direct inhibition of DNAM-1." (PMID 37345111, 2023). "A higher TIGIT expression has already been associated with the tumor microenvironment, correlating with metastasis and a poor prognosis." (PMID 36980196, 2023). "Nevertheless, upregulation of TIGIT in NK cells was associated with tumor progression in several studies and blocking TIGIT showed beneficial effects with the enhancement of NK cell effector functions." (PMID 37056774, 2023).
tumor (continued). "Our previous study identified several regulators of CD8 T cell function for which protein expression was regulated by loss of CD47 expression in the tumor microenvironment, including TIGIT, PD-1, CD39, CD62L, and CD127." (PMID 36768931, 2023). "Further studies with other tumor models with higher TIGIT expression are needed to fully evaluate the diagnostic potential of the anti-mTIGIT Nb tracer described in this study." (PMID 37799715, 2023). "Our result showed that all the immune checkpoints were high in the high-risk group except for TIGIT, suggesting that they synergistically regulated the immune response in the tumor microenvironment." (PMID 36778644, 2023). "Further, high TIGIT expression in tumor cells was found to be associated with favorable prognosis, but without statistical significance (p = 0.1680) (g)." (PMID 37573372, 2023). "A notable association was observed across risk score and the expression of CTLA4, HAVCR2, PDCD1, PDCD1LG2, and TIGIT, indicating risk scores represent tumor-induced immunosuppression." (PMID 37404760, 2023). "The deficiency of TIGIT in mice leads to uncontrollable T-cell responses and suppressed tumor growth." (PMID 36765704, 2023). "Increased expression of Siglec10, SIRPα, and TIGIT was significantly associated with the infiltration levels of neutrophils and dendritic cells (DCs) in almost all tumor types except THYM." (PMID 38016957, 2023). "A notable correlation was observed between risk score and expression of CTLA4, HAVCR2, PDCD1, PDCD1LG2, and TIGIT, indicating risk scores represent tumor-induced immunosuppression." (PMID 37404760, 2023). "Previous studies have reported that chronic inhibitory signaling promotes the exhaustion of cytotoxic immune cells and TIGIT has been associated with NK cell exhaustion in tumor-bearing mouse models and cancer patients." (PMID 37345049, 2023). "PD-1, CTLA4, CD96, and TIGIT are associated with each other in tumor immunity, which are candidates for immunotherapy." (PMID 36936375, 2023). "On the other hand, overexpression of TIGIT on tumor-infiltrating lymphocytes is associated with advanced stages of cancer." (PMID 36765704, 2023). "To understand the functional abnormalities in Ccl21a-KO intratumoral Tregs, we examined the expression of co-inhibitory receptors TIM-3 and TIGIT, which are associated with Treg function in the tumor microenvironment." (PMID 37664721, 2023). "Others observed that TIGIT expression on tumor-infiltrating NK cells was associated with tumor progression in preclinical models." (PMID 35008385, 2022). "In one such case, TIGIT was shown to be manipulated in patients suffering from colorectal cancer for the benefit of the tumor and its associated bacterial species, Fusobacterium nucleatum." (PMID 35513379, 2022). "In contrast to delayed tumor progression in TIGIT-/- and CD96-/-, CD226-deficient mice exhibit increased susceptibility to MCA-induced fibrosarcomas as well as metastatic lung colonization (e.g., LLC lung and RM-1 prostate tumors)." (PMID 35812451, 2022). "TIGIT blockade combined with low-dose OX lost the inhibition of tumor growth in CD8+ T deficient mice compared to that in untreated mice." (PMID 36389751, 2022). "Either NK deficient TIGIT or using Blockade of this inhibitor alone or combined with Blockade of PD-L1 significantly restored the suppressed anti-tumor immunity by NK cells in CRC animal models and patients." (PMID 36686835, 2022). "A combination of anti-TIGIT and anti-PD-L1 therapy significantly decreased tumor growth and alleviated weight loss in HNSCC-bearing mice." (PMID 36551992, 2022). "The research indicated that a high proportion of TIGIT+ Tregs and a high TIGIT/CD226 ratio in Tregs in the tumor immune microenvironment were associated with poor clinical prognosis." (PMID 35474948, 2022).